RN7SL186P (RNA, 7SL, cytoplasmic 186, pseudogene)
Gene: Miscellaneous RNA gene on chromosome 1 (22,010,650 to 22,010,946, forward strand). Ensembl gene ENSG00000278124.
Homologues: Orthologues: chimpanzee Metazoa_SRP (99% identical), macaque Metazoa_SRP (81% identical). Paralogues in human: RN7SL386P (99% identical), RN7SL1 (86% identical), RN7SL2 (86% identical), RN7SL3 (84% identical), RN7SL45P (84% identical), RN7SL126P (84% identical), RN7SL679P (82% identical), RN7SL712P (82% identical), RN7SL778P (82% identical), RN7SL296P (81% identical), RN7SL300P (81% identical), RN7SL383P (81% identical), and 702 more.